IL18 (interleukin 18)
Diseases named in the same sentence as IL18 in open-access papers (continued):
Sharing a sentence is not in itself a finding about the gene and the disease.
infection (continued). "Previously published data demonstrated increased activation of the NLRP3 inflammasome, caspase-1, caspase-5, IL-1β, IL-18 and gasdermin D after infection of C. acnes-infected nucleus pulposus tissue." (PMID 36761775, 2023). "Inflammasomes are multimeric protein complexes which assemble in immune cells upon disruption of cellular homeostasis (during infection or injury), and drive the processing and release of pro-inflammatory cytokines IL-1β and IL-18." (PMID 38129373, 2023). "IL18 is expressed constitutively in the gastrointestinal tract and is upregulated in response to infection by the gastric mucosal pathogen, Helicobacter pylori." (PMID 37365163, 2023). "Interleukin-18 (IL-18) is a pro-inflammatory cytokine involved in the immune response to infection and inflammation, produced by various cells, including macrophages, dendritic cells, and epithelial cells." (PMID 37304287, 2023). "rL. lactis treatment prior to infection with C. perfringens led to temporal and spatial changes in expression of IL-13, IL-17, IL-18, IL-22, IL-12p40 and IFN-γ to β-actin from week 1 onwards in all sites along the intestine." (PMID 38164397, 2023). "By directly sensing specific proteases required for infection, IL-18 allows keratinocytes to discriminate between numerous species with high virulence potential and common pathogen-associated molecular patterns and toxins." (PMID 37068092, 2023). "Interleukin (IL)-18 is an inflammatory cytokine that controls innate and adaptive immunity; it promotes host defense and inflammation after infection or injury." (PMID 37446301, 2023). "Second, IL-18 can further induce the secretion of downstream chemokines through the inflammatory cascade reaction, and promote their chemokines to the site of infection, further exacerbating the inflammatory response." (PMID 37636019, 2023). "Intriguingly, we found that while cytokines related to acute viral response returned to normal levels upon infection clearance, the inflammatory response mediated by IL-6 and IL-18 remained elevated for weeks to months past infection resolution." (PMID 37490342, 2023). "Neither ASC nor NLRP3 played a significant role in host defense against ST infection, and IL-18 release was unaffected in infected Nlrp3-/—mice." (PMID 37155697, 2023). "The NLRP3 inflammasome is a component of the inflammatory response to infection and injury, orchestrating the maturation and release of the pro-inflammatory cytokines interleukin-1β (IL-1β), IL-18, and triggering pyroptotic cell death." (PMID 38129373, 2023). "Despite this, the only cytokine for which there was a significant difference between the mice genotypes after infection was IL-18, being higher in Cish+/+ mice." (PMID 38029163, 2023). "During infection, the lungs employ physical barriers and immune cells that release inflammatory cytokines like IL-6, IL-1β, and IL-18, initiating the inflammatory response." (PMID 37686825, 2023). "Since IL-18 is produced upon infection of adult mice as well, we next investigated why NK cells are more responsive to IL-18 in young mice." (PMID 37828009, 2023). "Among the cytokines, IL-1β, IL-6, and IL-18 are known to be very important cytokines that respond to a PAK infection [36, -38]." (PMID 36788468, 2023). "shinshuense, infection with mycolactone F-producing M. pseudoshottsii exclusively induced IL-18 production, suggesting that the mycolactone-mediated suppression of cytokines is not an M. ulcerans-specific phenomenon." (PMID 37910490, 2023). "IL-18 is a potent pro-inflammatory cytokine which involved in host defense against infections and regulates the innate and acquired immune response." (PMID 37384047, 2023).
infection (continued). "Gene expression analyses showed that IL-18 and IL-34 genes were significantly (p <0.05) upregulated for both cell lines when exposed to mixed species infections." (PMID 37466528, 2023). "Infection induces several cytokines and chemokines, but keratinocytes constitutively secrete IL-18 in a form that is inert (pro-IL-18) and lacks proinflammatory activity." (PMID 37068092, 2023). "Correlation between the percentage of FAM-FLICA+ CD4+ (E), CD8+ (F) splenic cells and IL-18 plasma levels in vehicle treated HIV-1 infect group at day 22 post-infection." (PMID 36800238, 2023). "A significant correlation between increased circulatory IL-18 and decreased CD4 count suggests that IL-18 can be considered a potential biomarker of disease progression at the acute stage of infection." (PMID 36851142, 2023). "Our results are supported by other publications showing the induction markers by IL-18 in response to infection." (PMID 38140192, 2023). "By contrast, hvKp infection induced relatively low levels of Il1b and Il18 expression in these cells." (PMID 37457695, 2023). "The hepatitis E virus can cross the BBB in a TNF-α independent fashion and produce a productive infection in brain endothelial cells, increasing brain TNF-α and interleukin 18 (IL-18) levels that are associated with perivascular inflammation and gliosis." (PMID 36768699, 2023). "While IL22 seems to activate the cascade in response to an infection, IL18 is indispensable for the PC response and homeostasis." (PMID 36573340, 2023). "NLRP3 is the most characteristic inflammasome activated by the infection or stress reaction of cells, which is responsible for the maturation of pro-inflammatory cytokines IL-1β and IL-18." (PMID 36816025, 2023). "To validate the key role of IL-18-Stat3 signalling in Paneth cells during AIEC infection, we investigated how the injection of recombinant IL-18 into Defa6-Cre+Stat3f/f mice contributes to AIEC host defence." (PMID 35169117, 2022). "By immunofluorescence analysis of littermate mice, we also found that Olfm4+ crypt base columnar (CBC) stem cells are greatly reduced in both Il-22−/− and Il-18−/− crypts at the steady state or during AIEC infection 26,35." (PMID 35169117, 2022). "Being an acute-phase reactant, ferritin is regulated by proinflammatory cytokines (IL-6, IL-18), which levels increase during infection, cancer, and inflammatory conditions such as rheumatologic diseases." (PMID 35936656, 2022). "NF-κB signaling is responsible for the activation of several proinflammatory cytokines, such as (TNF-α), IL-6, and IL-18, which are important for infection control." (PMID 35453567, 2022). "On the contrary, IL-18 mRNA expression was shown to be considerably increased in the three infection groups, with statistically significant differences between the groups." (PMID 36556283, 2022). "Other cytokines (IL-5, IL-1, IL-6, and IL-18) were significantly higher in the intestine at early infection but became higher in the spleen as the infection progressed." (PMID 36187827, 2022). "In this regard, IL-18 was identified as one of the pivotal cytokines that regulate macrophage cells during this infection in supplement with IL-12, IL-27, IFNγ, and TNFα." (PMID 35885055, 2022). "When macrophages are activated by an antigen (such as infection source), they will secrete IL-18, and then chemotactic T cells will secrete IFN-γ." (PMID 35329948, 2022). "The recombinant LSDV Atyrau-5BJN(IL18) is safe for clinical use, immunogenic and protects animals from infection with the virulent LSDV." (PMID 36298570, 2022). "To provide in vivo evidence that IL-22 links IL-18 to upregulate T-cell production of IFNγ in response to AIEC infection, we first investigated how the injection of recombinant IL-18 into Il-22−/− mice contributes to host defence." (PMID 35169117, 2022). "To this end, we explored how loss of Il-22, Il-18, or epithelial Stat3 in mice affects stem cells at the steady state or during AIEC infection." (PMID 35169117, 2022).
infection (continued). "Analysis of the serum of P+ participants also revealed increases in IL-1Ra, IL-6, IFN-γ and IL-18, with the greatest differences observed at 72 h, consistent with a delay in the kinetics of the immune response from the site of infection to the blood." (PMID 35140232, 2022). "Mag-Pam2Cys_P48 treated moMΦ released higher levels of IL-1α, IL-1β, IL-1Ra, and IL-18 in response to infection with NH/P68 ASFV compared to 26544/OG10-infected and mock-infected controls." (PMID 36298767, 2022). "Meanwhile, rMukHN494+495JS also induced higher levels of IL-18 both in the spleen and thymus than rMukteswar throughout the infection, especially at 24 and 48 hpi in the thymus." (PMID 35711809, 2022). "Its initial discovery has been traced back to the last decade and IL-18 appears to contain unique characteristics, some of which can treat sepsis and infections (influenza, brain inflammation, and HSV-1)." (PMID 35891284, 2022). "Analysis of serum IL-18 showed that Gbp1–/– and Gbp3–/– mice had an impaired ability to produce this inflammasome-dependent cytokine following infection with F. novicida." (PMID 35906252, 2022). "The attenuated NH/P68 presented a reduced ability to infect moM1 compared with moMφ, and moM1 released IL-1α, IL-1β, and IL-18 in response to infection with this attenuated strain." (PMID 35215216, 2022). "The combination of the levels of inflammatory factors, IL-6 and IL-18, at the 0-hour postoperative time point, significantly improved the predictive ability to the development of postoperative infection during perioperative period." (PMID 36299462, 2022). "IL-1β, IL-8, and IL-18 are important cytokines regulating the inflammatory responses at the site of infection." (PMID 35587634, 2022). "Previous studies have reported that K-BCs mainly exert their anti-infection effects by secreting IL-12 and IL-18 through which K-BCs activate NK group I innate lymphoid cells." (PMID 39872747, 2022). "Inflammasomes are a molecular platform that are assembled to process pro-caspase 1 and subsequently promote secretion of interleukin (IL)-1β/IL-18 for proinflammatory responses induced upon infection." (PMID 35173184, 2022). "The inflammasome–caspase-1–IL-1/IL-18 axis is a relatively newly discovered innate immune pathway that is activated in response to infection and deleterious injury." (PMID 35740095, 2022). "In the priming step, expressions of NLRP3, pro-IL-1β, and pro-IL-18 are increased in response to stimuli, such as infection, injury, and ROS." (PMID 36289519, 2022). "Ki67+ crypts, more distributed in the TA compartments, were significantly reduced in Il-22−/− and Il-18−/− mice at the steady state or during AIEC infection." (PMID 35169117, 2022). "In vivo study showed that infection with Burkholderiaceae resulted in the release of IL-1β and IL-18, the expression of inflammasome components and the death of lung epithelial cells." (PMID 35401192, 2022). "Collectively, infection-induced changes in placental bed IL-18 and Htra1 involved cells that participate in spiral artery remodeling (i.e., uNK cells and endovascular invasive trophoblasts)." (PMID 36042379, 2022). "Of note, IL18 is upregulated at the onset of infection (dpi 1, 4), which is corresponding to that IL-18 is increased upon fever onset and remains highly elevated in the acute phase of SARS-CoV-2 infection in patients." (PMID 36825215, 2022). "Upregulation of NLRP3, IL-1β, and IL-18 was also demonstrated in primary isolated human bronchial epithelial cells after a 6-h infection with PAO1." (PMID 35215060, 2022). "In collaboration with IL-12, IL-18 activates the Th1-mediated immune response, participating in the host defense against infection." (PMID 36354688, 2022). "Interleukin-18 (IL-18) is a potent pro-inflammatory cytokine involved in host defense against infections and regulates the innate and acquired immune response." (PMID 36032110, 2022).
infection (continued). "Following infection with Citrobacter 7 days earlier, the expression of transcripts for proinflammatory cytokines Il1β, Il12, and Il18 and for immunoregulatory Il10 was increased." (PMID 35140345, 2022). "As noted, IL-18 expression in Il-22−/− ileum crypts was reduced at the steady state or during AIEC infection." (PMID 35169117, 2022). "The NLRP3 inflammasome is a multiprotein complex that regulates caspase‐1 activation and subsequent interleukin (IL)‐1β and IL‐18 release from innate immune cells in response to infection or injury." (PMID 35137954, 2022). "The NKB cells expanded for up to 24 h post-infection and these cells secreted a variety of cytokines (IL-6, IL-12, IL-15, IL-1β, and IL-18), suggesting important functions." (PMID 36405684, 2022). "Deletion of the subAB gene enhanced production of IL-1β and IL-18 even more, as demonstrated in the experiment on subAB-deficient STEC O113: H21 (STEC O113 ΔsubAB) infection." (PMID 35345462, 2022). "By GD18, infection-induced changes in placental bed IL-18, Htra1, and uNK cells were equivalent between control and infected groups." (PMID 36042379, 2022). "Regarding inflammatory response, ChP organoids showed an increase in inflammatory cytokines CCL7, interleukin-32 (IL-32), CCL2, MCP1, IL-18, and IL-8 upon infection." (PMID 35337041, 2022). "We conclude that mucosal AIEC infection triggers an early IL-22 response cascade which subsequently initiates an IL-18 response circuit." (PMID 35169117, 2022). "Infection with these clinical strains also led to caspase-1 activation in BMDMs and significant increases in IL-1β and IL-18 production." (PMID 35277504, 2022). "In order to trigger the innate immune system, IL-18 combines with IL-12, stimulating NK cells to respond to cancers and infections." (PMID 36032110, 2022). "Cytokines transcriptional trends revealed an immunosuppressive response during early infection stages, with decreased expression of some cytokines, such as IL-12, IL-4, IL-5, IL-1, IL-18, and IL-15, at 2 dpi, 4 dpi, or both compared to control." (PMID 36187827, 2022). "RT-qPCR showed that the mRNA levels of caspase-1/-4, Il-18 and Tnf-α were upregulated at 3 dpi, and continued to increase with ongoing infection." (PMID 35639503, 2022). "Intriguingly, we observed that Listeria expressing the SPI-2 needle protein SsaG induced significantly increased IL-18 and robust IL-1α and IL-1β secretion compared to mock infection or WT Lm infection alone." (PMID 35073381, 2022). "Upon infection, the inflammasome is activated, resulting in the production of IL-1β and IL-18, which recruits other immune cells to the site of infection." (PMID 35062292, 2022). "Considering the mouse response to infection by C. neoformans, the most highly upregulated transcripts after 6 h of infection were involved in recognition, uptake, and phagocytosis, including IL-18 and TNF." (PMID 36497155, 2022). "Interleukin-18 (IL-18) is an 18 kDa proinflammatory cytokine that plays important roles in the initiation and promotion of host defense and inflammation after infection or injury." (PMID 32918930, 2021). "Focusing on the IL-18 pathway, during IECs’ infection by HIV-1, the transactivator HIV Tat protein binds to TLR4-MD2-CD14 epithelial complex, activating the NF-κB pathway." (PMID 33801524, 2021). "We observed that infection with each strain induced a unique pattern of release of IL-1β and IL-18, implying that their engagements of inflammasomes are distinct." (PMID 35004352, 2021). "We observed that the deletion of the cryptococcal VLP1 gene did not affect the production of cytokines such as IL-2, INF-γ, Il-17A, and IL-18 in host blood in the early, middle, and late stages of infection." (PMID 34072011, 2021). "In conclusion, we found that pathogenic E. coli HPI infection of Yunnan Saba pigs upregulated the expression of NLRP3, caspase-1, IL-1β and IL-18 mRNA, and promoted cell membrane pore formation and nuclear DNA damage in macrophages." (PMID 33678162, 2021).
infection (continued). "The IL-1β and IL-18 levels in the LPS + ATP group were significantly higher than those in the control group at 0.5, 3 and 6 h post-infection (P < 0.01)." (PMID 33678162, 2021). "Taken together, these results demonstrate that IL-18 signaling is dispensable for the upregulation of nutrient transporters on NK cells during in vivo infection and inflammation." (PMID 34093543, 2021). "IL-1β and IL-18 levels were significantly increased in the peritoneal fluid of Mint3–/– mice 3 days after LM infection." (PMID 33854054, 2021). "After 24 h of infection, the relative expressions of TNFα, IL-8, and IL-18 mRNA in the ΔhtpG infection group were significantly lower than those in the WT infection and CΔhtpG infection groups (p < 0.05)." (PMID 34869065, 2021). "In the meantime, the inflammasome effectors including caspase-1, IL-1β, and GSDMD largely increased at infection; whereas IL-18 decreased during infection." (PMID 34161342, 2021). "Given the importance of IL-18 in NK cell activation and its elevated presence following nasal znBAZ infection, the role of IL-18 was investigated." (PMID 34305935, 2021). "Groups of BALB/c mice were treated by the i.p. route with either anti-IL-18 mAb or IgG isotype control one day prior to nasal znBAZ infection and every three days afterwards." (PMID 34305935, 2021). "Compared to peritoneal macrophages from WT mice, cleavage of caspase-1 and expression of IL-1β and IL-18 at both the mRNA and protein levels are reduced in the cells from Aim2-/- mice following infection with MTB." (PMID 33503864, 2021). "The expression of IL-1β and IL-18 mRNA in the three infection groups was higher than that in the control group at 6 and 9 h post-infection (P < 0.01), with the highest expression at 9 h post-infection." (PMID 33678162, 2021). "Early in infection, NK cells are primarily activated by cytokines such as type I interferons, interleukin-12 (IL-12), IL-15, and IL-18, secreted by macrophages and monocytes." (PMID 34305935, 2021). "Aim2 is a dsDNA sensor that upon recognition induces the formation of an inflammasome complex releasing IL1β and IL18 from the cell as a defense mechanism to control infection." (PMID 34047695, 2021). "F. novicida has served as a prototype for activation of the AIM2 inflammasome and it has been demonstrated that the infection leads to activation of caspase-1 and cleavage of the precursors of IL-1β and IL-18, thereby leading to their secretion." (PMID 35004352, 2021). "As for pro-inflammatory cytokines and chemokines, we observed that the transcripts of CCL5 (RANTES) increased significantly after infection whereas moderate increases of IL-18, IP-10 and TNF-α transcripts were detected in UT-SCC-60A cells." (PMID 33481814, 2021). "Analysis of proinflammatory cytokine/chemokine profiles during the acute phase of infection between days 14 and 16 post challenge showed marked increases of G-CSF, GM-CSF, IL-1β, IL-4, IL-8, IL-12/23 (p40), IL-18, MCP-1/CCL2, SCD40L, TGF-α, and VEGF." (PMID 34451491, 2021). "Twelve hours after infection, the levels of circulating inflammatory cytokines (IL-1β, IL-6, IL-18, and TNF-α) were still hardly detectable in most of the animals." (PMID 34236052, 2021). "Experimental colonization of germ-free mice by Prevotella promoted the decrease of IL-18 interleukin expression, neutrophil recruitment at the site of infection and gut inflammation." (PMID 34253752, 2021). "Three key proteins generally involved in infection and inflammation (IL6 IL18, and IFNG) are the focus of this analysis and are associated with 10 other proteins." (PMID 35145507, 2021). "Briefly, in a murine model of infection, Burkholderia is initially detected by macrophages through the Naip/Nlrc4 inflammasome, and the consequent IL-18 release triggers the production of IFN-γ whereby in neutrophils and macrophages, caspase-11 is upregulated." (PMID 34399626, 2021).